CD47 (CD47 molecule)
Diseases named in the same sentence as CD47 in open-access papers (continued):
Sharing a sentence is not in itself a finding about the gene and the disease.
myeloma (continued). "Disruption of CD47-TSP-1 interaction by TSP-1-blocking antibodies or down-regulation of CD47 on tumor cells by RNA interference abrogates tumor-induced osteoclast formation in multiple myeloma." (PMID 32677994, 2020). "Blocking CD47 with B6H12 antibodies increased phagocytosis of myeloma cells in vitro." (PMID 32677994, 2020). "CD47 was also consistently expressed in various myeloma cell lines." (PMID 32677994, 2020). "In myeloma, the potential importance of targeting CD47-TSP-1 axis has already been highlighted." (PMID 26046793, 2015). "Moreover, myeloma cell clones may directly prevent phagocytosis by TAMs via upregulation of the “don’t eat me” molecule CD47, which binds to the inhibitory receptor SIRPα expressed on macrophages." (PMID 37744361, 2023). "Therefore, the myeloma microenvironment which exists in 3DTEBM cultures may have contributed to the CD47 downregulation seen in 3DTEBM compared to 2D culture models." (PMID 32012878, 2020). "Meanwhile, THBS1/CD47 interactions also activate NF-κB–RANK ligand signaling to increase malignancy and metastasis in myeloma cells." (PMID 40988744, 2025). "We next assessed the in vivo antitumor killing efficacy of BsAbs targeting CD47 and CD38 in a mouse xenograft model using CB17-SCID mice implanted with the NCI-H929 multiple myeloma cell line." (PMID 38983860, 2024). "We also determined the expression of immune suppressive genes, and observed an increase in immune escape score and high expressions of CD47, LGALS1 and TGFB1 in low-immune response myeloma." (PMID 36717896, 2023). "SRF231 is a fully human IgG4 anti-CD47 antibody, which was previously granted orphan drug qualification by FDA for the treatment of patients with multiple myeloma." (PMID 34717705, 2021). "An analysis of patient samples with multiple myeloma (MM) (171 patients) and monoclonal gammopathy of undetermined significance (MGUS) (18 patients) showed that CD47 mRNA levels increased with progression from MGUS to MM." (PMID 32677994, 2020). "Pre-clinical studies already showed that combining daratumumab and CD47/SIRPα blockade could be a promising therapeutic approach for T-ALL and multiple myeloma." (PMID 36052078, 2022). "This clinical trial used CD47 mAb with or without dexamethasone plus an anti-myeloma regimen for the treatment of R/R MM." (PMID 35978372, 2022). "This work demonstrated that BCMA/CD47-directed UCAR-T cells exhibited potent antitumor activity against MM in vitro and in vivo, which provides a potential strategy for the development of a novel “off-the-shelf” cellular immunotherapies for the treatment of multiple myeloma." (PMID 38783333, 2024). "BCMA/CD47-directed UCAR-T cells demonstrated efficacy against MM and prolonged the survival of tumor-engrafted NCG mice in vivo, which provides a potential strategy for the development of a novel “off-the-shelf” cellular immunotherapies for the treatment of multiple myeloma." (PMID 38783333, 2024). "Of note, although for DLBCL the expression of SLAMF7 does not impact on phagocytosis upon CD47-targeting treatment, its impact especially in multiple myeloma (MM) may well be different." (PMID 30710089, 2019). "We tested the effect of co-culturing MM cells with myeloma-derived stromal cells MSP-1 on expression of CD47, and found that MM did not induce significant change in CD47 expression levels." (PMID 32012878, 2020).
osteosarcoma (38 papers, 2014 to 2026). A usually aggressive malignant bone-forming mesenchymal neoplasm, predominantly affecting adolescents and young adults. "Here the authors show that doxorubicin promotes IL-18 secretion by tumor associated macrophages inducing LAT2-dependent CD47 upregulation in osteosarcoma cells, suggesting LAT2 inhibition as a therapeutic option in combination with doxorubicin." (PMID 36274066, 2022). "Activating tumor-associated macrophages by inhibiting CD47 augmented the macrophage-mediated clearance of tumor cells and inhibited osteosarcoma growth and pulmonary metastases in mice." (PMID 36274066, 2022). "Here, we demonstrate that chemotherapy markedly enhances the expression levels of CD47 in osteosarcoma tissues, which are positively associated with patient mortality." (PMID 36274066, 2022). "Furthermore, we found that CD47 protein expression was associated with metastasis at the time of osteosarcoma diagnosis." (PMID 39594611, 2024). "Thus, we revealed a regulatory mechanism underlying CD47 upregulation in osteosarcoma after chemotherapy, which resulted in an innate immune escape and was associated with poor prognosis in osteosarcoma patients." (PMID 36274066, 2022). "Higher CD47 expression is associated with worse survival in osteosarcoma patients." (PMID 36274066, 2022). "Osteosarcomas express high levels of the surface marker CD47, which prevents their engulfment and clearing by tumour-associated macrophages (TAMs), and blocking CD47 in osteosarcoma xenografts has been found to inhibit tumour progression by activating tumour cell clearance by TAMs." (PMID 32961800, 2020). "Anthracyclines can mediate susceptibility to a blocking antibody against CD47, increase translocation of calreticulin to the cell surface, and intensify macrophage activity; in vivo studies have shown successful combination therapy against osteosarcoma." (PMID 35582455, 2020). "These associations suggest the potential utility of CD47 blockade in the treatment of osteosarcoma." (PMID 26093091, 2015). "CD48, TIMD-4, B7-H6, CD134, B7-H5, CD47, and S100A8/A9 were significantly elevated in osteosarcoma patients, each linked to increased osteosarcoma risk." (PMID 40963634, 2025). "In our study, elevated CD47 levels were observed in the plasma of metastatic osteosarcoma patients, suggesting a role in driving macrophage polarization toward the M2 phenotype." (PMID 40963634, 2025). "For instance, doxorubicin has been shown to modulate macrophage polarization into a more inflammatory state and increase CD47 expression on osteosarcoma cells." (PMID 40078999, 2025). "While limited studies are available on anti-CD47 CAR-NK cells, CAR-T cells targeting CD47 show great efficacy against ovarian, pancreatic, lung, and osteosarcoma models." (PMID 41511303, 2025). "Our primary aim was to delineate the expression profile of CD47 in osteosarcoma samples and investigate correlations between CD47 protein expression and various clinicopathological characteristics." (PMID 39594611, 2024). "A better understanding of the role of CD47 is necessary to develop an innovative immunotherapeutic approach against osteosarcoma." (PMID 39594611, 2024). "The CD47 antibody enhanced the phagocytic activity of MDMs towards osteosarcoma cells, further supporting its potential value in immunotherapeutic approaches for osteosarcoma." (PMID 39594611, 2024). "Our preliminary data suggest a possible interaction between CD47 protein and macrophage phagocytosis in osteosarcoma metastasis." (PMID 39594611, 2024). "We demonstrated that the CD47 antibody augmented the in vitro phagocytic activity of MDMs towards osteosarcoma cells." (PMID 39594611, 2024). "Herein, we evaluated the feasibility of targeting CD47 for osteosarcoma by analyzing its expression patterns, clinicopathological correlations, and immunotherapeutic potential." (PMID 39594611, 2024).
osteosarcoma (continued). "KHOS/NP, MG-63, and U-2 OS cells were treated with the CD47 antibody (B6H12) to assess the effect of the antibody on osteosarcoma cells." (PMID 39594611, 2024). "The association between CD47 protein expression and clinical characteristics in biopsy tissues, along with the enhanced phagocytic activity towards osteosarcoma cells by the CD47 antibody, suggests the potential value of CD47 in osteosarcoma immunotherapy." (PMID 39594611, 2024). "Several studies have indicated that there are high levels of CD47 in osteosarcoma cells and that osteosarcomas can be inhibited by aCD47." (PMID 38560565, 2024). "Despite its limitations, the findings of our study lay the groundwork for understanding the role of CD47 in osteosarcoma and suggest an innovative immunotherapeutic approach against this malignancy." (PMID 39594611, 2024). "Our preliminary exploration suggests the promising potential of using CD47 as a novel target for osteosarcoma immunotherapy." (PMID 39594611, 2024). "Here, we prepared a dual pH-sensitive nanocarrier, loaded with the photosensitizer Chlorin e6 (Ce6) and CD47 monoclonal antibodies (aCD47), to deliver synergistic photodynamic and immunotherapy of osteosarcoma." (PMID 38560565, 2024). "Despite the limitations of our study, the findings provide valuable groundwork for a better understanding of the role of CD47 in osteosarcoma and suggest an innovative immunotherapeutic approach against this formidable malignancy." (PMID 39594611, 2024). "KHOS/NP osteosarcoma cells were labeled with carboxyfluorescein succinimidyl ester and pretreated with B6H12 antibody to assess the potential enhancement of macrophage-mediated phagocytosis in osteosarcoma cells mediated by the CD47 antibody." (PMID 39594611, 2024). "Although data on CD47 expression and its correlation with the clinical outcomes of osteosarcoma are limited, we suggest the possibility of CD47 protein expression as a prognostic marker of osteosarcoma." (PMID 39594611, 2024). "The phagocytic activity of MDMs on KHOS/NP osteosarcoma cells was higher in cells pretreated with the CD47 antibody, exhibiting a 3.2-fold increase compared with those pretreated with the isotype antibody (p = 0.0016)." (PMID 39594611, 2024). "We performed a retrospective analysis on 24 biopsy samples from patients with osteosarcoma to investigate correlations between CD47 protein positivity and clinicopathological characteristics." (PMID 39594611, 2024). "This study aimed to evaluate the feasibility of CD47 as a potential therapeutic target for osteosarcoma." (PMID 39594611, 2024). "Of the 24 osteosarcoma biopsy samples, 5 (20.8%) exhibited positive staining for CD47, with staining intensities categorized as high and low in 2 and 3 samples, respectively." (PMID 39594611, 2024). "combined anti-GD2 therapy with anti-CD47 therapy, which upregulated calreticulin expression on the surface of osteosarcoma cells, respectively, as well as promoting phagocytosis of osteosarcoma cells by macrophages." (PMID 39916962, 2024). "In vivo studies should be performed using a mouse model of osteosarcoma established previously to elucidate the correlation between CD47 expression and metastasis in osteosarcoma cell lines." (PMID 39594611, 2024). "We have shown previously that a tumor-suppressing protein, CALR, inhibited the progression of osteosarcoma cells via interaction with CD47." (PMID 37056934, 2023). "The team investigates mice with orthotopically implanted murine or human osteosarcomas and treats them with CD47 mAb or IgG1 control antibody." (PMID 36961012, 2023). "Results have shown stronger hypointense (dark) nanoparticle enhancement of intratibial osteosarcomas after treatment with CD47 mAb compared with IgG1 control antibody." (PMID 36961012, 2023). "The enhanced Gln/Leu uptake stimulates the activation of mTORC1/c-Myc signaling to promote the expression of CD47 and leads to an inhibited macrophage phagocytosis of osteosarcoma cells." (PMID 36274066, 2022).
osteosarcoma (continued). "In this study, we find that CD47 is upregulated in osteosarcoma in response to chemotherapy, and this upregulation is associated with patient mortality." (PMID 36274066, 2022). "In another recent study, a possible synergistic effect of the combination of anti-GD2 and anti-CD47 antibodies has been reported in syngeneic mouse models of neuroblastoma and osteosarcoma." (PMID 36297471, 2022). "Inhibition of LAT2-mediated CD47 upregulation in osteosarcoma cells augments macrophage phagocytosis and sensitized tumor cells to chemotherapy." (PMID 36274066, 2022). "In the Therapeutically Applicable Research to Generate Effective Treatments (TARGET) osteosarcoma cohort, patients with higher CD47 expression also showed higher M1 abundance." (PMID 36274066, 2022). "GSEA analysis of TARGET osteosarcoma data showed that cell metabolism, including amino acid metabolism, was enriched in patients with high CD47 expression." (PMID 36274066, 2022). "Depletion of LAT2 or treatment of tumor cells with a LAT inhibitor downregulates CD47 with enhanced macrophage infiltration and phagocytosis of tumor cells, and sensitizes osteosarcoma to doxorubicin treatment in mice." (PMID 36274066, 2022). "We next evaluated the outcomes of the chemotherapy based on the expression of CD47 in osteosarcoma patients." (PMID 36274066, 2022). "The expression of CD47 (H-score) was significantly increased in the post-chemotherapy specimens compared to the paired pre-chemotherapy counterparts, suggesting that chemotherapy promotes CD47 expression in osteosarcoma." (PMID 36274066, 2022). "In osteosarcoma, CD47 is usually expressed at higher levels in the cancer cells than in the surrounding normal tissue." (PMID 36274066, 2022). "CD47 expression was observed in approximately 53% of osteosarcoma cells, whereas SIRPα expression was identified in approximately 32% of the infiltrating macrophages." (PMID 33802565, 2021). "Accordingly, the combination of CD47 mAb and doxorubicin significantly reduced tumour size and prolonged survival in osteosarcoma tumour-bearing mice compared to animals receiving either monotherapy or control IgG." (PMID 32961800, 2020). "It was reported that CD47 was overexpressed in human osteosarcoma samples of different types than normal bone tissue or osteoma samples." (PMID 33363016, 2020). "It has been confirmed that CD47 blockade by specific antibodies promotes the phagocytic effects of macrophages on osteosarcoma cells." (PMID 33363016, 2020). "Similar to the preclinical studies in other tumors, CD47 can represent a useful therapeutic target in osteosarcoma." (PMID 33363016, 2020). "In patients with osteosarcoma, increased CD47 mRNA expression and protein levels were found in tumor samples compared with paired normal tissue, which correlated with decreased progression-free and overall survival." (PMID 35582455, 2020). "We evaluated if ferumoxytol-enhanced MRI can monitor TAM response to CD47 mAb therapy in osteosarcomas." (PMID 30674867, 2019). "Confirming this process, we found that CD47 mAb triggered macrophage phagocytosis and tumoricidal effects in osteosarcomas and reduced tumor burden in vivo." (PMID 30674867, 2019). "We found that CD47 messenger RNA (mRNA) expression, as determined by quantitative real-time PCR (qPCR), was significantly higher in human osteosarcoma specimen as compared to osteoma and normal bone specimen (p < 0.001)." (PMID 30674867, 2019). "Many osteosarcoma cells overexpress the surface marker CD47, which acts as a ‘don't eat me signal’ for TAM." (PMID 31376208, 2019). "CD47 is a cell-surface molecule on osteosarcoma cells that function as a “don’t eat me” signal by engaging signal-regulatory protein alpha (SIRPα), an inhibitory receptor on macrophages." (PMID 30674867, 2019). "show that blockade of CD47 by specific Abs suppresses the invasive ability of osteosarcoma tumor cells and further inhibits spontaneous pulmonary metastasis of KRIB osteosarcoma cells in vivo." (PMID 31376208, 2019).
osteosarcoma (continued). "Doxorubicin is established for the treatment of osteosarcomas and acts on a common mechanistic pathway with CD47 mAb by inducing immunogenic cell death." (PMID 31376208, 2019). "In conclusion, our study introduces a new and immediately clinically translatable imaging biomarker for TAM response in osteosarcomas to CD47 mAb therapy." (PMID 30674867, 2019). "As a prerequisite for planned immunotherapies with CD47 blocking antibodies, we first confirmed that human osteosarcomas express CD47." (PMID 30674867, 2019). "In conclusion, CD47 mAb plus doxorubicin therapy demonstrates an additive therapeutic effect in mouse models of osteosarcomas, which can be monitored with an immediately clinically applicable MRI technique." (PMID 31376208, 2019). "CD47-expressing osteosarcoma specimens showed significantly (p < 0.001) higher levels of TAM markers CD68 and CD163 compared to osteomas and normal bones." (PMID 30674867, 2019). "In the presence of CD47 mAb, F4/80+ macrophages displayed a three- to five-fold increase in phagocytosis of Saos-2 osteosarcoma cells relative to control antibody-treated macrophages." (PMID 30674867, 2019). "For example, Doxorubicin is established for the treatment of osteosarcomas and acts on a common mechanistic pathway with CD47 mAb by inducing immunogenic cell death." (PMID 31695797, 2019). "Immunofluorescence staining confirmed that CD47 protein levels of all osteosarcoma patient specimens were significantly (p < 0.001) higher compared to osteomas and normal bone." (PMID 30674867, 2019). "We found that CD47 mAb triggered macrophage phagocytosis and tumoricidal effects in osteosarcomas and reduced tumor burden in vivo." (PMID 31376208, 2019). "Forty-eight osteosarcoma-bearing mice were treated with CD47 mAb or control IgG and underwent pre- and post-treatment ferumoxytol-MRI scans." (PMID 30674867, 2019). "(2015), and our own team previously reported overexpression of CD47 on osteosarcoma cells and efficacy of CD47 mAb against human osteosarcomas in mouse models." (PMID 31376208, 2019). "The purpose of our study was to compare the efficacy of CD47 mAb plus doxorubicin combination therapy in mouse models of osteosarcoma with CD47 mAb and doxorubicin monotherapy." (PMID 31376208, 2019). "In this study, we explored the use of antibodies that block CD47 with a tumor growth suppressive effect on osteosarcoma." (PMID 26093091, 2015). "In this study, we found that CD47+ cells have higher capacity in osteosarcoma tumorigenicity and metastasis, when compared with CD47− counterparts." (PMID 26093091, 2015). "We found that up-regulation of CD47 mRNA levels and protein levels in the osteosarcoma tissues when compared with those of normal osteoblastic cell lines and adjacent non-tumorous tissues." (PMID 26093091, 2015). "To determine if CD47 mRNA expression levels were a prognostic factor in patients with osteosarcoma, we analyzed gene-expression data from a cohort of 30 patients with osteosarcoma." (PMID 26093091, 2015). "To find how CD47 expression was regulated during different stages of osteosarcoma, we characterized CD47 reactivity in 40 paraffin-embedded osteosarcoma samples with different degrees of invasive behavior (20 osteosarcoma samples)." (PMID 26093091, 2015). "We provided evidence that antibody that block CD47 is a potential and effective treatment for osteosarcoma in vivo." (PMID 26093091, 2015). "Osteosarcoma cancer stem cell markers staining shown that the majority of CD44+ cells expressed CD47 albeit with different percentages (ranging from 80% to 99%)." (PMID 26093091, 2015). "Future studies will address the ability of anti-CD47 Abs to eliminate established osteosarcoma metastases before and following surgical resection of the primary tumor, mimicking treatment of metastatic disease in the clinical setting." (PMID 26093091, 2015).